KL (klotho)
Diseases named in the same sentence as KL in open-access papers (continued):
Sharing a sentence is not in itself a finding about the gene and the disease.
diabetic retinopathy (4 papers, 2020 to 2025). "A schematic model was developed to illustrate the regulatory mechanism of Klotho in diabetic retinopathy (DR)." (PMID 41438297, 2025). "For the study of diabetic retinopathy (DR) and cardiovascular complications, although some results are heterogeneous, the overall trend still supports the protective effect of Klotho." (PMID 41438297, 2025). "Diabetic retinopathy shares similar pathological mechanisms with DN, and targeting klotho may offer new insights into the prevention and treatment of both conditions." (PMID 37143722, 2023). "Klotho may be a novel biomarker of diabetic retinopathy and a potential treatment target for diabetic eye disease." (PMID 33225726, 2020). "There is limited information on Klotho and diabetic retinopathy in the literature." (PMID 33225726, 2020).
glioma (4 papers, 2019 to 2025). A benign or malignant brain and spinal cord tumor that arises from glial cells (astrocytes, oligodendrocytes, ependymal cells). "In our study, we analyzed two Klotho gene polymorphisms (rs1207568 and rs564481) in glioma patients and healthy controls." (PMID 39796185, 2025). "Our results suggest the impact of Klotho genetic variants and Klotho levels on advanced-grade glioma." (PMID 39796185, 2025). "The association of Klotho rs1207568 and rs564481 polymorphisms with overall survival (OS) in patients with gliomas was also examined." (PMID 39796185, 2025). "While Klotho’s role in tumorigenesis is well-established, its association with specific glioma-related genetic variants remains unexplored." (PMID 39796185, 2025). "Stratification of the glioma patients into subgroups according to grade have shown statistically significant differences in the Klotho rs1207568 (-395G/A) allele and genotype distributions." (PMID 39796185, 2025). "Therefore, our study aimed to investigate the association between Klotho gene polymorphisms (rs1207568 and rs564481) and overall survival in glioma patients." (PMID 39796185, 2025). "However, after stratification of patients into subgroups according to glioma grades, we found statistically significant differences in the Klotho rs1207568 (-395G/A) allele and genotype distributions." (PMID 39796185, 2025). "By analyzing genomic DNA isolated from peripheral blood samples, we found that stratifying glioma patients into subgroups according to glioma grades has shown statistically significant differences in Klotho rs1207568 (-395G/A) allele and genotype distributions." (PMID 39796185, 2025). "We attempted to identify the role of the aging-suppressor Klotho gene and Klotho protein in the immunopathogenesis of gliomas." (PMID 39796185, 2025). "We are only at the beginning of our journey to fully understand the role of Klotho in gliomas and other brain tumors." (PMID 39796185, 2025). "We analyzed the serum level of soluble alfa Klotho protein in a group of patients with gliomas and healthy controls." (PMID 39796185, 2025). "However, only limited data exist on Klotho’s role in gliomas." (PMID 39796185, 2025). "We cannot compare our results with findings from other studies because, to our knowledge, the serum Klotho was not analyzed in glioma patients until now." (PMID 39796185, 2025). "Given the limited research on Klotho’s role in glioma and the absence of studies examining serum αKlotho levels in this context, our study aimed to fill these knowledge gaps." (PMID 39796185, 2025). "Interestingly, among Klotho genes, only LCTL met the preset criterion and was significantly upregulated in both brain lower grade glioma (LGG) and GBM, as compared to levels in normal tissue (p < 0.05)." (PMID 31681612, 2019).
hypertriglyceridemia (4 papers, 2016 to 2025). A laboratory test result indicating elevated triglyceride concentration in the blood. "In addition, genetic variants of Klotho have been associated with insulin resistance and hypertriglyceridemia." (PMID 30943913, 2019).
memory impairment (4 papers, 2015 to 2024). "In addition, upregulation of the klotho ameliorate ageing-related memory impairment and decreased oxidative damage in senescence-accelerated model mice." (PMID 36819720, 2023). "This might explain why chronic administration of ligustilide prevents (via klotho upregulation) the development of AD-like neuropathologies and memory impairment." (PMID 26599613, 2015).
multiple sclerosis (4 papers, 2018 to 2025). A progressive autoimmune disorder affecting the central nervous system resulting in demyelination. "A study showed that serum Klotho concentration is higher in multiple sclerosis patients with a longer disease duration when compared to the control group." (PMID 37425590, 2023). "The present paper is a short review of the literature on the role of Klotho in neurodegenerative disorders, with special attention paid to multiple sclerosis." (PMID 30062646, 2018). "Thus, remyelination by Klotho modulation can be another potential target for the generation of new therapeutics for multiple sclerosis." (PMID 37425590, 2023).
Myocardial fibrosis (4 papers, 2018 to 2025). "In conclusion, secreted Klotho alleviated myocardial fibrosis by activating NRF2 to promote GR expression." (PMID 35721561, 2022).
pancreatic ductal adenocarcinoma (4 papers, 2020 to 2025). An infiltrating adenocarcinoma that arises from the epithelial cells of the pancreas. "We aimed to study the role of klotho as a tumor suppressor in pancreatic ductal adenocarcinoma (PDAC)." (PMID 34944918, 2021). "Within the context of pancreatic ductal adenocarcinoma, high expression of miR-504 has been shown to correlate with low levels of Klotho, and miR-504 inhibition resulted in Klotho re-expression." (PMID 32585905, 2020).
preeclampsia (4 papers, 2021 to 2025). Preeclampsia is a hypertensive disorder of pregnancy that is characterized by new-onset hypertension with proteinuria presenting after 20 weeks of gestation, and depending on mild or severe forms may initially present with severe headache, visual disturbances, and hyperreflexia. "Low circulating maternal and foetal levels of Klotho are associated with preeclampsia, intrauterine growth restriction, and an increased perinatal risk for newborns, indicating a potential use of Klotho as biomarker and therapeutic target." (PMID 38486352, 2024). "The connection between Klotho and preeclampsia has been extensively studied, and Klotho is being considered as a potential marker for diagnosis and treatment." (PMID 39940672, 2025). "While Klotho is also involved in preeclampsia, placental aging and preterm delivery, to our knowledge, a possible interaction of Klotho with HIF in regulation of placental function, preeclampsia or preterm delivery has not yet been studied." (PMID 38486352, 2024). "Klotho has been suggested as a diagnostic tool for several pregnancy-associated diseases, including intrahepatic cholestasis of pregnancy (ICP), preeclampsia and gestational diabetes." (PMID 38486352, 2024). "In another study, comparing 36 women with preeclampsia versus 28 healthy women and 10 with chronic hypertensive pregnancy, serum Klotho above 12.48 pg/mL identified the presence of preeclampsia with a sensitivity of 100% and specificity of 96%." (PMID 38486352, 2024). "To determine the correlations of Klotho levels with the development of preeclampsia (PE), we initially collected the maternal and umbilical cord serum from normal participants, PE pregnancy with or without small for gestational age infant (PE-SGA)." (PMID 38632651, 2024). "The connection between preeclampsia and aging is supported by research on the Klotho gene, an anti-aging protein that appears to play a pivotal role during the intrauterine period and may influence long-term health outcomes." (PMID 39940672, 2025). "Additionally, a significant downregulation of soluble Klotho (sKlotho) was observed in the urine of women with preeclampsia compared to healthy controls." (PMID 39940672, 2025). "Nevertheless, accelerated aging of the placenta due to lower Klotho expression may be involved in preeclampsia and/or IUGR." (PMID 38486352, 2024). "Thus, Klotho may influence preeclampsia pathogenesis by modulating the Nrf2/ARE pathway." (PMID 39940672, 2025).
temporal lobe epilepsy (4 papers, 2013 to 2025). A localization-related (focal) form of epilepsy characterized by recurrent seizures that arise from foci within the temporal lobe, most commonly from its mesial aspect. "In summary, Klotho exerted neuroprotection against epilepsy-associated cognitive deficits by inhibiting ferroptosis in a LiCl Pilo-induced temporal lobe epilepsy rat model." (PMID 37124220, 2023). "As observed in a Temporal Lobe Epilepsy rat model, Klotho overexpression significantly reduced iron overload, increased glutathione peroxidase-4 (GPX-4) and glutathione (GSH) levels, and decreased reactive oxygen species (ROS) in the hippocampus." (PMID 40351444, 2025). "A recent study showed that the anti-aging protein Klotho improved cognitive deficits in a rat model of temporal lobe epilepsy by inhibiting ferroptosis." (PMID 37124220, 2023). "Additionally, Klotho significantly increased glutathione peroxidase-4 and glutathione levels while suppressing reactive oxygen species levels in a rat model of temporal lobe epilepsy." (PMID 38203812, 2024).
amyotrophic lateral sclerosis (3 papers, 2020 to 2025). Amyotrophic lateral sclerosis (ALS) is a neurodegenerative disease characterized by progressive muscular paralysis reflecting degeneration of motor neurons in the primary motor cortex, corticospinal tracts, brainstem and spinal cord. "Previously, it was observed that in an amyotrophic lateral sclerosis (ALS) model, Klotho overexpression delayed disease onset, reduced neuronal loss, and decreased inflammation." (PMID 40351444, 2025).
and bone metabolism disorders (3 papers, 2016 to 2020). "Briefly, FGF23-Klotho signaling axis is a pivotal regulator of mineral and bone metabolic disorder in CKD–MBD." (PMID 33708111, 2020). "FGF23-Klotho signaling axis is reported to be useful for regulating mineral and bone metabolic disorder in CKD–MBD." (PMID 33708111, 2020). "Consequently, targeting FGF23-Klotho signaling axis in response to renal injury and its correlative mineral and bone metabolic disorder has been identified as multi-targets in the treatment of CKD–MBD." (PMID 33708111, 2020).
Anxiety (3 papers, 2018 to 2023). Intense feelings of nervousness, tension, or panic often arise in response to interpersonal stresses. "Furthermore, the sex differences in the CUMS-induced deficit in spatial learning and memory, anhedonic-like behaviors, and anxiety-like behaviors decreased when the levels of endogenous KL protein reduced in the rat hippocampus of both sexes." (PMID 36674721, 2023). "However, 2-week CUMS induced a deficit in spatial learning memory, anhedonic-like behaviors, and anxiety-like behaviors in both female and male rats when endogenous KL levels reduced using KL-shRNA." (PMID 36674721, 2023). "Data found diets such as high-protein, low-calorie, low-calorie high-protein diets increased Klotho/FGF23 signaling in the brain, and consequently, Klotho could enhance neuronal plasticity factors and enhance memory and anxiety." (PMID 33072166, 2020). "In this study, we also found that NBP may have therapeutic effects on anxiety and depressive behavior by increasing Bdnf and Klotho mRNA level in pilocarpine-induced epileptic mice." (PMID 30050437, 2018). "Consequently, we speculate the therapeutic function of NBP in chronic epileptic comorbidities associated with anxiety and depressive behavior by increasing the expression level of BDNF and Klotho." (PMID 30050437, 2018). "Since KL is associated with cognition and stress response, the next experiment was to determine whether the CUMS-induced deficit in spatial learning and memory, anhedonic-like behavior, and anxiety-like behavior in male rats is accompanied by an alteration in KL expression in the hippocampus." (PMID 36674721, 2023). "CUMS produced a deficit in spatial learning and memory, anhedonic-like behaviors, and anxiety-like behaviors in male but not female rats, which was accompanied by a reduction in KL protein levels in the hippocampus of male but not female rats." (PMID 36674721, 2023). "A CUMS-mediated decrease in the level of KL protein in the hippocampus of male but not female rats is accompanied by a deficit in spatial learning and memory, anhedonic-like behaviors, and anxiety-like behaviors in males only." (PMID 36674721, 2023). "Two-week CUMS did not alter cognitive function, anhedonic-like behaviors, and anxiety behaviors in the rats of both sexes when endogenous KL levels were intact." (PMID 36674721, 2023). "To the best of our knowledge, we showed for the first time that the specific knockdown of KL in the rat hippocampus does not induce a clear deficit in spatial learning and memory, anhedonic-like behaviors, and anxiety-like behaviors in males and females." (PMID 36674721, 2023). "In this study, the CUMS-induced deficit in spatial learning and memory, and anhedonic-like and anxiety-like behaviors in male rats was accompanied by a decrease in the levels of KL protein in the hippocampus of male but not female rats." (PMID 36674721, 2023).
aortic stenosis (3 papers, 2016 to 2024). Aortic valve stenosis is a aortic valve disease caused by the incomplete opening of the aortic valve. "It is known that serum levels of Klotho decrease after age 40, while the prevalence of aortic stenosis increases with age." (PMID 27242197, 2016). "Our study provides the first experimental evidence that Klotho deficiency is a pathological factor for AVF, which is an important remodeling process that causes aortic valve stiffening, eventually leading to aortic valve calcification and aortic stenosis." (PMID 27242197, 2016). "Thus, an additional study is warranted for assessing the effect of administration of recombinant Klotho protein on aging‐related aortic stenosis." (PMID 27242197, 2016). "These novel findings suggest a novel role of FGF23 in the pathogenesis of CAVD associated with CKD and point to the therapeutic potential of Klotho for prevention of CAVD development and progression in old CKD subjects with high risks for CAVD and aortic stenosis." (PMID 38993571, 2024).
Brain atrophy (3 papers, 2022 to 2024). Partial or complete wasting (loss) of brain tissue that was once present. "Mice with klotho deficiency showed brain atrophy learning difficulties a reduction in hippocampal synapses, axonal transport problems, hippocampus neurodegeneration and demyelination." (PMID 38468203, 2024). "Fibroblast growth factor (FGF)-23 (a hormone produced mainly by osteocytes in response to high serum phosphate levels) and Klotho (an obligate coreceptor of FGF-23) were hypothesized to be associated with brain atrophy in AUD." (PMID 35558424, 2022). "These actions may explain the anti-senescence effects of Klotho, providing theoretical support to the findings of the inverse relationship between Klotho and brain atrophy." (PMID 36009045, 2022). "Notably, unlike Klotho, they did not observe a significant relationship between FGF-23 levels and brain atrophy in AUD; FGF-23 levels were not inversely related to the bifrontal index." (PMID 35558424, 2022).
brain injury (3 papers, 2022 to 2025). Acute and chronic (see also brain INJURIES, CHRONIC) injuries to the brain, including the cerebral hemispheres, CEREBELLUM, and brain STEM. "Klotho is a pleiotropic protein that was proven to play a protective role against ischemic brain injury and to circulate in high concentrations in the plasma of acute stroke patients, correlating also with better functional outcomes." (PMID 37175644, 2023). "Although no studies have been published regarding the relationship between artichoke and Klotho and PPARγ activity, recent studies demonstrated that phenolic compounds have neuroprotective effects in brain injuries by upregulating Klotho and PPARγ expression." (PMID 36556233, 2022).
cerebral infarction (3 papers, 2019 to 2022). An ischemic condition of the brain, producing a persistent focal neurological deficit in the area of distribution of the cerebral arteries. "We aimed to investigate the expression of Klotho gene in peripheral blood of patients with cerebral infarction (CI) and the association of its polymorphisms with the occurrence of CI." (PMID 35510207, 2022). "First, we did not analyze Klotho variants and the size of cerebral infarction volumes." (PMID 33376748, 2020).
clear cell renal cell carcinoma (3 papers, 2020 to 2025). "Inconsistent with our results, a study of clear cell renal cell carcinoma found preoperative serum Klotho to be associated positively with cancer-specific and progression-free survival; as a retrospective single-center study considering very limited covariates, the evidence was low quality." (PMID 40696614, 2025).
congestive heart failure (3 papers, 2018 to 2022). Failure of the heart to pump a sufficient amount of blood to meet the needs of the body tissues, resulting in tissue congestion and edema. "The associations among Klotho (exposure), congestive heart failure (CHF; outcome), and renal function markers [estimated glomerular filtration rate (eGFR), blood urea nitrogen (BUN), uric acid (UA), and urine albumin-to-creatinine ratio (UACR); mediators] were investigated using mediation analysis." (PMID 35509269, 2022). "Here, we analyzed the association of FGF23 and sKlotho upon progression of chronic heart failure (CHF) and analyzed Klotho expression in human hearts." (PMID 29849175, 2018).
coronary stenosis (3 papers, 2020 to 2023). Narrowing of the coronary artery lumen diameter. "Besides, we previously reported that patients with significant CAD present lower soluble Klotho levels and, also, that soluble Klotho concentration is independently and negatively associated with the severity of the coronary stenosis." (PMID 31986490, 2020). "However, within the group of patients with T2DM, those subjects with CAD presented significantly higher Klotho levels than those without significant coronary stenosis (314.5 (6.15–562.81) vs. 458.97 (275.2–667.2) pg/mL; p = 0.02)." (PMID 37686263, 2023).
diffuse large B-cell lymphoma (3 papers, 2017 to 2021). "Overexpression of Klotho in diffuse large B cell lymphoma (DLBCL) cell lines, LY1 and LY8, resulted in increased apoptosis and inhibition of proliferation." (PMID 32585905, 2020). "We aimed to explore the expression pattern and functional mechanism of Klotho in diffuse large B cell lymphoma (DLBCL)." (PMID 28153033, 2017). "Enhancing the expression of anti-aging genes can be an effective way to inhibit lymphoma, a recent study showed that enforced expression of Klotho could significantly induce cell apoptosis and inhibit tumor growth in diffuse large B-cell lymphoma (DLBCL)." (PMID 33885377, 2021).